PRRT2 (proline rich transmembrane protein 2)
Diseases named in the same sentence as PRRT2 in open-access papers (continued):
Sharing a sentence is not in itself a finding about the gene and the disease.
Dystonia (15 papers, 2013 to 2025). An abnormally increased muscular tone that causes fixed abnormal postures. "All 3 children with homozygous PRRT2 variants had a SeLIE phenotype with normal development and comorbid movement disorders (i.e., dyskinesias and dystonia)." (PMID 40401013, 2025). "Since it is already known that single gene disorders, including SCN1A, SCN2A, KCNQ2, PRRT2, and pyridoxine deficiency, can result in isolated dystonia, we add CdLS5 (HDAC8 variation) to this expanding spectrum." (PMID 38910710, 2024). "It is already known that single gene disorders, including SCN1A, SCN2A, KCNQ2, PRRT2, and pyridoxine deficiency, can result in isolated dystonia; we add CdLS5 (HDAC8 variation) to this expanding spectrum." (PMID 38910710, 2024). "For example, Ca2+ channelopathy, Prrt2-deficient, and Pnkd mutant mice are characterized by dystonia, chorea, and tonic-clonic episodes." (PMID 35819138, 2022). "The patient had a paternal mutation of the PRRT2 gene—his father had symptoms of dystonia in his youth—and the software predicted the likely pathogenicity of the mutation." (PMID 35715422, 2022). "PDK is caused by mutations in the gene encoding for proline-rich transmembrane protein 2 (PRRT2), presenting clinically with brief sudden onset unilateral or bilateral attacks of dystonia and chorea that is brought on by sudden movements." (PMID 32775036, 2020). "Compared to non-PRRT2-related PKD, in PRRT2-mutation carriers the age at onset is earlier, the episodes last longer and occur with higher frequency, phenomenology of attacks more frequently combines both dystonia and chorea and lower carbamazepine doses (50–100 mg/day) are effective." (PMID 32443735, 2020). "PKD patients with PRRT2 mutations (PKD‐M) show distinct clinical manifestations including earlier age of onset and longer duration of attacks, complex phenotypes of dystonia and chorea, and more tendency for a family history compared to PKD patients without PRRT2 mutations (PKD‐N)." (PMID 32592228, 2020). "Importantly, the phenotypes associated with mutations in the DYT genes enriched in the putamen ‘cyan’ module belonged to different clinical subtypes of dystonia, namely isolated dystonia (ANO3 and HPCA), combined dystonia (KCTD17 and ADCY5), and paroxysmal dystonia (KCNA1, CACNA1A, PRRT2 and SCN8A)." (PMID 32889528, 2020).
ICCA syndrome (13 papers, 2012 to 2022). "The combination of BFIS and PKD (ICCA syndrome) is associated with mutations in PRRT2 in about 80% of cases, whereas isolated PKD is associated with PRRT2 mutations in 40–90% of cases." (PMID 33833732, 2021). "Mutations in the PRRT2 gene are associated with various neurological seizure-inducing disorders, including PKD, BFIE, and familial infantile convulsions with paroxysmal choreoathetosis (infantile convulsions and choreoathetosis, ICCA)." (PMID 36467477, 2022).
Ataxia (11 papers, 2016 to 2025). Ataxia refers to impaired coordination of voluntary muscle movement. "Two of these individuals were found to harbour pathogenic/likely pathogenic variants in GCH1 and PRRT2, respectively, although these findings were of uncertain clinical relevance to the cerebellar ataxia phenotype." (PMID 40007153, 2025). "Slower traverse time was noted in homozygous knockout mice only, consistent with the ataxia seen in rare individuals with biallelic loss of function mutations in Prrt2." (PMID 34101060, 2021). "Fortunately, in contrast to previously reported cases, development in our girl remains age-appropriate at four years, despite the bi-allelic loss of PRRT2 and three episodes of ataxia from mild head trauma." (PMID 33126500, 2020). "A similar dramatic reduction and slowdown of evoked release was present in a mouse strain bearing a destabilizing Syt2 mutation and exhibiting ataxia, one of the manifestations of PRRT2 mutations in patients." (PMID 27052163, 2016). "EA is a clinically heterogeneous disorder characterized by recurrent spells of ataxia lasting minutes to hours which has been associated over time to a number of genes besides CACNA1A and KCNA1 (CACNB4, SLC1A3, FGF14, SLC2A1, ATP1A3, PRRT2) accounting for the majority of cases." (PMID 32823520, 2020).
Choreoathetosis (9 papers, 2016 to 2024). Involuntary movements characterized by both athetosis (inability to sustain muscles in a fixed position) and chorea (widespread jerky arrhythmic movements). "It is worth mentioning that a Chinese patient had a predominant phenotype of choreoathetosis attacks and additional signs of myotonia, with the coexistence of a PRRT2 mutation and two CLCN1 mutations." (PMID 38091244, 2024). "Movement disorders are salient features of PRRT2-associated conditions, usually with onset in adulthood, and consisting principally in dystonia and choreoathetosis." (PMID 35350397, 2022). "Notably, not only PKD but also other neurological disorders including benign family infantile epilepsy and infantile convulsions with choreoathetosis, are associated with PRRT2 mutations." (PMID 38091244, 2024). "Studies of the genotype-phenotype correlation have revealed that PKD patients with PRRT2 mutations tend to present with an earlier onset, a longer attack duration, the choreoathetosis phenotype, bilateral limb involvement, and more forms of dyskinesia than patients without PRRT2 mutations." (PMID 38091244, 2024).
Dyskinesia (9 papers, 2013 to 2025). A movement disorder which consists of effects including diminished voluntary movements and the presence of involuntary movements. "Focal-onset epilepsy in adolescence was diagnosed in another child with a heterozygous pathogenic PRRT2 variant and dyskinesias (case 38)." (PMID 40401013, 2025). "A breakthrough study showed that Prrt2 deficiency facilitated the induction of spreading depolarization (SD) in the cerebellar cortex and dyskinesia under KCl stimulation." (PMID 38091244, 2024). "In Prrt2-deficient mice, blocking the Nav channels reduced excessive parallel fiber excitability and prevented the cerebellar SD and the following dyskinesia." (PMID 38091244, 2024). "We believe that our findings make many significant contributions to current understanding of the molecular, cellular and circuit mechanisms underlying PRRT2-related dyskinesia." (PMID 29056747, 2018). "Although mutant mice are unlikely to match precisely the clinical symptoms of PKD, we did observe spontaneous dyskinesia attacks in some PRRT2-deficient mice under natural conditions." (PMID 29056747, 2018). "Spontaneous dyskinesia attacks occur in some Prrt2-deficient mice under natural conditions, consisting of a collection of various abnormal movements." (PMID 29056747, 2018). "Here we performed a circuit-level investigation to link the PRRT2 deficiency-caused synaptic phenotypes with mouse dyskinesia phenotypes." (PMID 29056747, 2018). "Thus, local ablation of PRRT2 in the vermis of the cerebellum increased susceptibility to hyperthermia-induced dyskinesia, strongly supporting an important role of cerebellar PRRT2 in movement disorders." (PMID 29056747, 2018). "Here, we report our findings in heterozygous and homozygous Prrt2 knockout mice that recapitulate the age dependence of dyskinesia seen in the human disease." (PMID 34101060, 2021). "Intriguingly, in vivo light stimulation of ChR2 in AAV-infected cerebellar neurons induces dyskinesia in GluN2C-iCre;Prrt2−/− mice, indicating that a PRRT2 function within cerebellar GCs is critical for normal movement control." (PMID 29056747, 2018). "Thus, our work provides a specific circuit-level mechanism underlying PRRT2-related behavioral phenotypes in which specific ablation of pre-synaptic PRRT2 in GCs facilitated transmission at PF-PC synapses, leading to enhanced PC firing and attacks of dyskinesia in the mutant mice." (PMID 29056747, 2018). "Significantly, Prrt2loxP/loxP mice with AAV-Cre-mediated knockout of PRRT2 in the midline cerebellum displayed hyperthermia-induced dyskinesia." (PMID 29056747, 2018). "In contrast to the intense dyskinesia found in all GluN2C-iCre;Prrt2−/− mice, hyperthermia hardly induced dyskinesia attacks in CaMKIIα-iCre;Prrt2−/− mice." (PMID 29056747, 2018). "For the first time, we have generated several experimental mouse models mimicking PRRT2-related dyskinesia manifested in human patients, including thermal elevation, kindling or PTZ-induced seizures, and optogenetic stimulation." (PMID 29056747, 2018). "Taken together, these results indicate that specific ablation of PRRT2 in GCs can induce abnormal spiking activity of PCs, accounting for the dyskinesia attacks." (PMID 29056747, 2018). "Notably, conditional knockout of Prrt2 in GCs was sufficient to induce dyskinesia attacks under hyperthermia stimulation." (PMID 38091244, 2024). "The absence or low expression of PRRT2 due to mutations in the PRRT2 may result from the loss of a transmembrane domain, which renders PRRT2 unable to anchor to membranes; such changes in PRRT2 may lead to hyperexcitability and trigger dyskinesias." (PMID 31722684, 2019). "Taken together, these results confirm that cerebellum is a key region for PRRT2-related dyskinesia." (PMID 29056747, 2018). "Together, these results identify the cerebellum as a key region for PRRT2-related dyskinesia." (PMID 29056747, 2018).
Dyskinesia (continued). "Notably, hyperthermia-induced dyskinesia occurred in all mice harboring the AAV-Cre-mediated PRRT2 deletion." (PMID 29056747, 2018). "In addition, GluN2C-iCre;Prrt2−/− mice, with selective deletion of PRRT2 in cerebellar GCs also generate optogenetic-induced dyskinesia phenotypes similar to Prrt2Stop mutant mice." (PMID 29056747, 2018). "Importantly, we found that the cerebellum is a key area mediating the function of PRRT2 in controlling movement, as revealed by the observation that conditional knockout of Prrt2 gene in cerebellar granule cells (GCs) was sufficient to induce dyskinesia attacks." (PMID 29056747, 2018). "To further elucidate the circuit mechanism underlying PRRT2-related dyskinesia in the cerebellum, we generated a mouse line (GluN2C-iCre;Prrt2−/−) with ablation of PRRT2 in cerebellar GCs, but not in other cerebellar cells, by crossing Prrt2loxP/loxP mice with GluN2C-iCre mice." (PMID 29056747, 2018). "Instead, in 2018, Tan and colleagues generated mouse models with global and cerebellum-specific Prrt2 truncation, but not forebrain, displaying dyskinesia attacks resembling human PKD." (PMID 38091244, 2024). "Meanwhile, CaMKII-iCre;Prrt2−/− mice with ablation of PRRT2 in forebrain could not be induced to develop dyskinesia by optogenetic stimulation of the cerebellum, PTZ injection and hyperthemia." (PMID 29056747, 2018).
infantile epilepsy (8 papers, 2019 to 2025). "We present a series of 40 patients from Germany, Switzerland, and Denmark with PRRT2-related benign infantile epilepsy and rarely reported associated comorbidities, further expanding the phenotypic spectrum." (PMID 33126500, 2020). "Based on a cohort of children with PRRT2-related infantile epilepsy, this study aimed at delineating the broad clinical spectrum of PRRT2-associated phenotypes in these children and their relatives." (PMID 33126500, 2020). "Moreover, the most prevalent genetic diagnoses for infantile epilepsy, particularly for patients aged < 12 months, were KCNQ2, PRRT2, and SCN1A." (PMID 35720076, 2022). "Importantly, sodium channel blockers, such as OXC and carbamazepine, have proven to be efficacious in PRRT2- and KCNQ2-related infantile epilepsies." (PMID 35720076, 2022). "Because at that time, the relationship between self-limited family infantile epilepsy and PRRT2 was not clear." (PMID 32246320, 2020). "Genetic studies have implicated heterozygous loss-of-function mutations in PRRT2 with infantile epilepsy and paroxysmal movement disorders (MIM: 605751and 128200), however it is not known what the impact of a PRRT2 gain-of-function may be." (PMID 36808153, 2023).
Seizure (8 papers, 2014 to 2025). A seizure is an intermittent abnormality of nervous system physiology characterized by a transient occurrence of signs and/or symptoms due to abnormal excessive or synchronous neuronal activity in the brain. "Seizures associated with PRRT2 mutations can also occur in the context of febrile seizures or febrile seizures plus syndrome (GEFS+)." (PMID 33833732, 2021). "Seizures associated with mutations in PRRT2 most commonly manifest as BFIS, with mean onset at 6 months but ranging between 3 and 20 months of age." (PMID 33833732, 2021). "PRRT2 variants were probably involved in the etiology of febrile seizures in epileptic patients." (PMID 25522171, 2014). "The PRRT2 mutation has been predominantly related to individuals and families with a wide group of early onset paroxysmal disorders such as PKD and different types of benign infantile seizures." (PMID 31801583, 2019). "To date, heterozygous PRRT2 mutations have been found in a multitude of patients with BFIE, ICCA, Paroxysmal Non-Kinesigenic Dyskinesia (PNKD), Paroxysmal Exertion-induced Dyskinesia (PED), childhood absence epilepsy and febrile seizures." (PMID 27449084, 2016).
episodic kinesigenic dyskinesia (7 papers, 2012 to 2025). Paroxysmal kinesigenic dyskinesia (PKD) is a form of paroxysmal dyskinesia, characterized by recurrent brief involuntary hyperkinesias, such as choreoathetosis, ballism, athetosis or dystonia, triggered by sudden movements. "Familial paroxysmal kinesigenic dyskinesia (PKD) is caused by PRRT2 mutations, but a distinct etiology has been suggested for sporadic PKD." (PMID 22752065, 2013). "Mutations in the PRRT2 gene have recently been identified in patients with familial paroxysmal kinesigenic dyskinesia with infantile convulsions (PKD/IC) and patients with sporadic PKD/IC from several ethnic groups." (PMID 22870186, 2012). "Additionally, PRRT2, a transmembrane protein linked to episodic kinesigenic dyskinesia 1155, displays increased expression due to DDX5." (PMID 41333436, 2025).
familial hemiplegic migraine (7 papers, 2015 to 2024). A migraine disorder characterized by individual and family history of aura that includes motor weakness. "On the other hand, mutations in the four genes (CACNA-1A, ATP1A2, SCN1A, and PRRT2) identified in patients with familial hemiplegic migraine (FHM) are associated with a reduced threshold value of cortical spreading depression, which is also responsible for auras." (PMID 37048668, 2023). "During recent years, other movement disorders and familial hemiplegic migraine (FHM) have been reported in single cases and a small series of patients harboring PRRT2 variants." (PMID 33126500, 2020). "Other paroxysmal disorders associated with PRRT2 include: PED, PNKD, paroxysmal torticollis, EA and familial hemiplegic migraine (FHM), which may co-exist with PKD or occur independently." (PMID 34177764, 2021). "Even though the involvement of three genes has been established in the onset of FHM, new research suggests the involvement of a fourth gene, PRRT2, in the rise of familial hemiplegic migraine." (PMID 38731230, 2024).
convulsion (6 papers, 2012 to 2023). A rapid and repeated body muscle contract that results in an uncontrolled shaking of the body. "All three familial patients with histories of infantile convulsions carry PRRT2 mutations." (PMID 22870186, 2012). "A de novo heterozygous PRRT2 deletion was identified in a child who had infantile convulsions induced by vigorous sucking." (PMID 35959395, 2022).
epilepsy syndrome (6 papers, 2014 to 2025). A syndrome that has a characteristic cluster of clinical features and/or lectroencephalographic (EEG) findings that reflect underlying epileptic activity. "However, recent studies suggested that pathogenic PRRT2 mutation could be responsible for some severe epileptic syndromes." (PMID 34041212, 2021). "Recent advancement of molecular genetics identified PRRT2 mutations are the most common genetic etiology of PKD, which could cause epilepsy syndromes as well." (PMID 30386286, 2018). "PRRT2 mutations, the most common genetic etiology of PKD, could cause epilepsy syndromes as well." (PMID 30386286, 2018).
autism (5 papers, 2014 to 2024). Persistent deficits in social interaction and communication and interaction as well as a markedly restricted repertoire of activity and interest as well as repetitive patterns of behavior. "Alterations in activity of Prrt2 have been found in the frontal cortex of individuals with autism and have also been genetically-associated with ASD." (PMID 25225482, 2014). "Although microdeletions and duplications at 16p11.2, where the PRRT2 gene is located, have been observed in patients with autism." (PMID 34041212, 2021). "Thus, we postulated that PRRT2 mutations play no pathological role in the development of autism in this patient." (PMID 34041212, 2021). "Current studies have found no clear relationship between PRRT2 pathogenic mutation and autism." (PMID 34041212, 2021). "Taken together, these results indicate that mutations in PRRT2 are not a frequent cause of autism." (PMID 24594579, 2014).
breast carcinoma (5 papers, 2000 to 2025). "Interestingly, breast cancer cell (MDA-MB-231)-derived EVs carry miR-454 and disrupt the Wnt pathway by targeting proline-rich transmembrane protein 2 (PRRT2), thereby promoting CSC stemness and ovarian cancer cell growth in vivo." (PMID 40182121, 2025).
Epileptic encephalopathy (5 papers, 2019 to 2025). A condition in which epileptiform abnormalities are believed to contribute to the progressive disturbance in cerebral function. "Do the epileptic seizures of a 6-month-old infant occur in the context of developmental and epileptic encephalopathy, or in the context of PRRT2-associated benign epilepsy (OMIM #605751), in which seizures are confined to infancy ?" (PMID 36672771, 2022). "Using a targeted epileptic encephalopathy (EE) panel, we identified a heterozygous variant of uncertain significance (VUS) in the gene PRRT2." (PMID 31801583, 2019). "We considered that the PRRT2 gene was the causative gene of EIMFS, suggesting that PRRT-2 spectrum diseases could also manifest as a very severe epileptic encephalopathy phenotype, but after effective treatment, the disease process could be quickly reversed and the prognosis was good." (PMID 35715422, 2022).
gallbladder carcinoma (5 papers, 2020 to 2023). "In gallbladder carcinoma, miR-30b inhibits the proliferation, metastasis, and invasion of cancer cells by targeting ecto-5′-nucleotidase (NT5E) and proline-rich transmembrane protein 2 (PRRT2)." (PMID 35291564, 2022).
channelopathy (4 papers, 2015 to 2024). Channelopathies are a group of diseases caused by the dysfunction of ion channel subunits or their interacting proteins. "In addition, thec.649dupC hotspot mutation may cause PKD by down regulating of PRRT2 mRNA, and it may be that PKD is not a channelopathy disease." (PMID 26621826, 2015). "Based on abnormal ion channels and disturbed synaptic transmission in the absence of PRRT2, PKD may be channelopathy or synaptopathy, or both." (PMID 38091244, 2024).
developmental delay (4 papers, 2020 to 2025). "In our cohort, several genes were frequently implicated in cases of genetic epilepsy and developmental delay, including PRRT2 (n:2), KCNQ2 (n:2), SCN1A (n:2), PLA2G6 (n:2), and KDM6A (n:2)." (PMID 40083435, 2025).
prostate carcinoma (4 papers, 2017 to 2025). A carcinoma that arises from epithelial cells of the prostate gland. "The PC346C prostate cancer cell line is the only cell line we identified, which has a mutation in both PRRT2 alleles." (PMID 27907910, 2017). "Both PRRT2 and DAB2IP were mutated in three out of the four MSI prostate cancer cell lines." (PMID 27907910, 2017).
autism spectrum disorder (3 papers, 2014 to 2025). A spectrum of developmental disorders that includes autism, and Asperger syndrome. "Furthermore, 1 child with a heterozygous PRRT2 variant and SeLIE (case 27) was diagnosed with autism spectrum disorder." (PMID 40401013, 2025).